INS (insulin)
Diseases named in the same sentence as INS in open-access papers (continued):
Sharing a sentence is not in itself a finding about the gene and the disease.
Obesity (continued). "The susceptibility of C57BL/6J mice to diet-induced obesity is typically characterized by changes in plasma insulin and leptin levels and insulin sensitivity at 6 weeks of age." (PMID 37007087, 2023). "Significantly lower HSP72 protein expression in skeletal muscle was associated with increased obesity and decreased insulin sensitivity in healthy subjects." (PMID 36978903, 2023). "Fibre has been associated with weight loss and insulin response independently of macronutrient and caloric intake in subjects with obesity." (PMID 38140329, 2023). "This study aimed to determine the association of dietary insulin index (DII) and dietary insulin load (DIL) with cardiometabolic risk factors among Iranian adults with obesity." (PMID 37226148, 2023). "Functional analysis showed that miR-122 is associated with IR, inflammation, and obesity development in individuals with overweight and regulates insulin signaling pathways." (PMID 37537674, 2023). "Obesity in particular is associated with dysregulation of lipid metabolism and insulin signaling pathways." (PMID 36875069, 2023). "The increased risk for hypertension among individuals with obesity is believed to be mediated by the activation of the sympathetic nervous system, increased insulin resistance, and the release of adipokines." (PMID 36821504, 2023). "While a complete loss of leptin causes impaired glucose homeostasis leading to obesity and a T2D phenotype, liver-specific leptin knockout in mice increases lipid accumulation in the liver but increases insulin sensitivity." (PMID 36769005, 2023). "Based on these studies, obesity has been identified as one of the major causes for the development of neuropathology, and altered insulin/IGF signaling contributes to obesity-related AD." (PMID 36691085, 2023). "We further show that impairment of metabolic signalling (such as impairment of insulin sensitivity in obesity) causes deficiencies in associative learning." (PMID 37592007, 2023). "The metabolic syndrome is a cluster of cardiovascular risk factors, including obesity, alterations in glucose-insulin metabolism, hypertension, and dyslipidemia." (PMID 38004175, 2023). "Women with early‐onset GDM have more clinical risk factors, and they are more insulin resistant already in early pregnancy compared with normoglycemic women with obesity." (PMID 36484476, 2023). "Several studies have identified genetic associations between single nucleotide polymorphisms (SNPs) and obesity and BC risk, implicating elevated insulin levels, impaired glucose metabolism, and dyslipidemia in BC risk." (PMID 37512149, 2023). "For example, the available studies have shown that the development of inflammation and reduced insulin sensitivity in the course of obesity are associated with reduced levels of adiponectin." (PMID 37373485, 2023). "This allowed us to differentiate between the molecular effects of obesity-associated insulin hypersecretion of β-cells (db/db.BKS mice at 6 weeks of age) and T2D-associated β-cell failure (db/db.BKS mice at 12 weeks of age) on the same genetic background." (PMID 36543979, 2023). "None of these genetic variants were associated with insulin Matsuda ISI, obesity, or glucose or insulin concentrations." (PMID 36837886, 2023). "The increased secretion of inflammatory cytokines derived from adipocytes is associated with reduced insulin sensitivity in obesity." (PMID 38136211, 2023). "The excess adipose tissue accumulation in obesity is associated with the release of adipokines, which are hormone-like mediators that control insulin sensitivity and energy balance." (PMID 37446154, 2023). "A multielemental analysis of plasma samples enabled us to comprehensively investigate the association between the insulin secretion profile and changes in circulating metal species among children and adolescents with obesity and IR." (PMID 37242230, 2023).
Obesity (continued). "Deregulation of insulin signaling not only explains several metabolic aspects of PCOS—independently of the associated obesity—but contributes to modulating ovarian steroidogenesis towards a stable “androgenic” phenotype." (PMID 37047265, 2023). "Serum apelin level is increased in obesity and insulin-resistant status, whereas apelin deficiency increases adiposity and blood fatty acid levels, and apelin overexpression is resistant to obesity." (PMID 37670786, 2023). "It significantly blocked several pathological events that are associated with diet-induced obesity in mice, such as lipid accumulation, development of fatty liver, and decreased insulin sensitivity." (PMID 37143889, 2023). "Overweight and obesity are associated with increased morbidity and mortality risk of MM through inflammatory cytokines, leptin, insulin, and insulin-like growth factor levels." (PMID 36910611, 2023). "Clinical and preclinical studies to date have implicated obesity-induced alterations in the levels of insulin, gastrointestinal peptide hormones, and adipocyte-derived hormones (adipokines) in PDAC development." (PMID 37648285, 2023). "Nonetheless, both aging and increased obesity are related to inflammatory conditions which impair insulin sensitivity and are associated with reduced skeletal muscle mass." (PMID 36695760, 2023). "In human trials acupuncture emerges as a potentially effective complementary treatment of obesity as it is thought to induce loss of appetite, down-regulates insulin and leptin resistance, and lowers ghrelin as well as glucose levels." (PMID 37795371, 2023). "Research has linked BPA exposure to T2DM, altered insulin release, obesity, and changes in the mass and function of insulin-secreting β-cells." (PMID 38021644, 2023). "LPL, the third most frequently selected protein, is also associated with obesity and other metabolic disorders related to energy balance, insulin action and body weight regulation." (PMID 37329449, 2023). "Obesity-associated metabolic disturbances can impair the function of the pancreas, particularly in insulin-secreting β-cells and it has been unequivocally proven in prior studies that β-cell mass reduces before the development of T2D." (PMID 37842639, 2023). "These metabolites contribute to obesity by affecting insulin sensitivity, altering energy balance, and causing low-grade inflammation." (PMID 37512528, 2023). "Obesity can cause an increase in both leptin and insulin levels, contributing to insulin resistance." (PMID 38130527, 2023). "Recent studies have shown that SH2B1, a gene implicated in leptin and insulin signaling, is a substantial contributor to the genetic architecture of obesity." (PMID 38434247, 2023). "Several studies recently focused on the possible role of dietary insulin index and insulin load in the prediction of cardiometabolic risk factors, such as hyperglycemia, dyslipidemia, IR, and obesity, which indicates interesting findings." (PMID 37069259, 2023). "A “worse” adipocyte morphology (hypertrophy), which is characteristic of obesity, has been linked with fasting plasma insulin levels and insulin sensitivity." (PMID 37764752, 2023). "Previous evidence suggested that obesity in children and adolescents was associated with unhealthy levels of blood fat, insulin, and blood pressure." (PMID 37383395, 2023). "Conditions that are associated with both CVD and heightened MSNA (e.g., obesity, hypertension and elevated insulin; Kalil & Haynes, 2012) are common comorbidities in females with PCOS." (PMID 37642329, 2023). "Inversely, obesity and smoking can decrease insulin absorption, fat hypertrophy or obesity leads to reducing insulin absorption, and smoking can cause peripheral vasoconstriction and delays insulin absorption." (PMID 37077814, 2023). "The results showed that BSDF significantly improved the phenotypic symptoms associated with obesity caused by weight gain, lipid accumulation, insulin resistance and inflammatory response." (PMID 36969828, 2023).
Obesity (continued). "T2D is often linked to lifestyle factors such as obesity and physical inactivity but can be managed through diet, exercise, medication, or insulin therapy." (PMID 37600709, 2023). "Functional disorders of insulin signaling in DM, obesity, and other metabolic disorders can be one of the causes of reproductive dysfunctions and reduced fertility." (PMID 36834685, 2023). "Specifically, lifestyle interventions are associated with enhanced glycemic control and insulin sensitivity as observed in persons with obesity and T2D." (PMID 38068805, 2023). "Decreased tissue sensitivity to leptin leads to obesity and is closely linked to insulin insensitivity." (PMID 36899958, 2023). "Studies exploring the role of metabolic alterations related to obesity has supported the risk and indicated that elevated insulin levels resulting from obesity-related insulin play a vital factor." (PMID 37697301, 2023). "CVD risk factors, including hypertension and obesity, have consistently been linked to cognitive decline through an array of interrelated mechanisms including impaired insulin sensitivity and elevated inflammation." (PMID 36541028, 2023). "This tumor-suppressive effect is lost in insulin/leptin resistant models (e.g., obesity-induced models), which predisposes to the development of cancer." (PMID 37672200, 2023). "Although contraindicated during pregnancy, these anti-obesity drugs simultaneously improve insulin sensitivity, reduce cardiovascular disease risk, and show promising potential in achieving and maintaining weight loss." (PMID 36675355, 2023). "The metabolic changes associated with obesity, particularly circulating levels of hormones such as leptin, insulin, and ghrelin, seem to negatively affect the olfactory function of individuals." (PMID 36837824, 2023). "Then, we will describe the molecular mechanisms underlying the obesity–cancer link, including inflammation, estrogens, insulin signaling, and adipokines." (PMID 37509120, 2023). "Skeletal muscle is the major source of glucose disposal, and unlike muscle mass increase that comes through exercise, increased skeletal muscle mass in obesity is associated with decreased insulin sensitivity." (PMID 38134035, 2023). "Gpx1 knockout (Gpx1−/−) with associated increased ROS production led to enhanced insulin signalling and protected mice from high-fat diet-induced obesity and metabolic impairment." (PMID 37238003, 2023). "In this diet, high fiber intake leads to reduction in the levels of LDL, cholesterol, triglycerides, hypertension, CRP, and the risk of obesity and overweight, and improves insulin sensitivity and endothelial function." (PMID 36911829, 2023). "Decreased glucose transport across the blood–brain barrier and into neurons—caused by obesity, older age, hyperglycemia, insulin resistance, or reduced neurotransmitter signaling—can drive a starving brain into dysfunction." (PMID 37760862, 2023). "As obesity and glucose intolerance are linked to changes in glucose-metabolizing and insulin-signaling genes, we measured changes in some representative markers in the WT and three KO lines." (PMID 37895206, 2023). "The etiological factors of hypertension include hemodynamic disturbances accompanying obesity, an increased peripheral vascular resistance associated with an impaired endothelial cell function, an insulin resistance, and the adipokines’ influence." (PMID 36674022, 2023). "In the last decade, several studies have reported that alterations in gut microbiome composition are associated with obesity, glucose metabolism, and insulin sensitivity." (PMID 37471410, 2023). "In particular, overweight and obesity were associated with increased C-peptide concentration and reduced insulin sensitivity, but unchanged glucose concentrations, compared to normal weight pregnant women." (PMID 37029207, 2023).
Obesity (continued). "These comorbidities are common in patients with obesity, and weight loss can reduce blood pressure, improve insulin sensitivity, and blood sugar control, improve sleep apnea syndrome, and reduce all these comorbidities." (PMID 36721216, 2023). "There are seven types of SIRTs, from SIRT1 to SIRT7, of which SIRT1 is linked to obesity and controls the genetic expression of insulin secretion and sensitivity and adipose tissue formation and facilitates inflammatory responses." (PMID 38203349, 2023). "Epigenetic programing predisposes pigs to insulin insensitivity, but pigs seem to sense this insensitivity and consequently eat less, preventing obesity." (PMID 36984860, 2023). "Obesity is often accompanied by insulin dysregulation (ID) that is strongly linked to equine metabolic syndrome (EMS) and laminitis." (PMID 37152686, 2023). "SORBS1 has been shown to be involved in the lipid metabolism and other studies have proven that SORBS1 is associated with obesity and insulin signaling." (PMID 37686221, 2023). "Women with PCOS often present glucose and energy homeostasis disruptions, along with obesity and metabolic syndrome, which arise associated with raised circulating levels of leptin and insulin." (PMID 37493841, 2023). "Transcriptomic analysis of these tumours revealed that insulin signalling and inflammation were the possible mechanisms that underly the prognostic effect of obesity on ER+ BC." (PMID 37173907, 2023). "Our results show that obesity caused an increase in intraocular pressure anda decrease in ocular pulse amplitude independently of insulin resistance inchildren and adolescents." (PMID 35319649, 2023). "It should be remembered that IGF-1 belongs to obesity-associated adipokines, proteins that along with leptin, insulin and IL-6 are also produced by adipocytes." (PMID 36835075, 2023). "Contrary to ApN, resistin levels increase in obesity, and it has been proposed as a risk factor for dementia, as it counteracts the effects of insulin and promotes inflammation in obesity." (PMID 37732123, 2023). "High levels of Adiponectin, a regulator of insulin sensitivity and lipid metabolism, have previously been associated with low body weight and weight loss, while low levels have been associated with obesity." (PMID 37045997, 2023). "In diet-induced obese mice, SCFA supplementation reduces body weight, improves insulin sensitivity, and reduces obesity-associated inflammation." (PMID 38037591, 2023). "Catch-up growth (especially in terms of body weight) has been shown to increase the occurrence of some cardiometabolic risk factors, including resistance to insulin, overweight, and obesity, already in childhood." (PMID 38004175, 2023). "A recent study investigating the gut microbiota patterns associated with insulin sensitivity in males with overweight or obesity concluded that the gut microbiota varied greatly between cohorts." (PMID 37189387, 2023). "Patients with T2D and obesity are thought to have a higher risk of developing complications from COVID-19 due to underlying chronic inflammation affecting glucose regulation and insulin sensitivity." (PMID 37374918, 2023). "For example, moderate L‐lactate administration, in high‐fat diet obese mice, reduced body weight and obesity‐associated insulin resistance." (PMID 37653564, 2023). "In our study, we found that OGG1 was upregulated in adipose tissue from participants with obesity in comparison with healthy participants and associated with insulin levels, indicating a role in obesity and insulin sensitivity in the human context." (PMID 36982562, 2023). "We identified lipid signatures linked with cardiometabolic risk factors including body weight change, pre-pregnancy obesity and glucose homeostasis and insulin resistance with potential implications both in pregnancy and postpartum life." (PMID 36782297, 2023).
Obesity (continued). "Considering that obesity is associated with hyperinsulinemia, we tested if insulin stimulates m6A methylation in these transcripts." (PMID 37526326, 2023). "Mechanically, we found that FGF21 LKO reduced circulating insulin levels, thus causing the dissociation between decreased central obesity and the improvement of obesity-related metabolic syndromes in OVX mice." (PMID 37834368, 2023). "Obesity in mice and humans disrupt this homeostatic immune cell balance and cause insulin resistance and adipose tissue inflammation." (PMID 37197653, 2023). "Both obesity and age-related neurodegenerative disorders are associated with dysfunctional insulin signaling, suggesting a potential link." (PMID 37934726, 2023). "Obesity-induced inflammation in adipose tissues causes insulin signaling impairment, leading to insulin resistance." (PMID 36838843, 2023). "Previous studies showed that obesity-associated adipose tissue inflammation is a major cause of decreased insulin sensitivity seen in T2D." (PMID 37047308, 2023). "Obesity is associated with an inflammatory cytokine milieu in the adipose tissue that eventually abrogates insulin sensitivity and promotes beta cell death." (PMID 37830559, 2023). "The main cause of T2DM is obesity-driven IR combined with inadequate secretion of insulin by pancreatic β cells." (PMID 37071471, 2023). "Age, educational level, prescription of insulin, hypertension and obesity were positively associated with the attendance of follow-up care and also significantly with age of the women." (PMID 37758812, 2023). "While T1DM is primarily the result of autoimmune destruction of pancreatic beta cells, T2DM is characterized by the loss of insulin sensitivity, deficiency in insulin secretion and is frequently linked to obesity." (PMID 37034348, 2023). "Our data suggest that apoA-IV deficiency in female 129X1/SvJ mice results in obesity, insulin insensitivity, and decreased energy expenditure under 16-week HFD." (PMID 37960308, 2023). "In conclusion, short-term ILI leads to a consequential improvement in NAFLD indices in patients with T1D and obesity and is associated with a reduction in insulin requirements." (PMID 37046323, 2023). "We examined the association between inflammatory biomarkers and insulin sensitivity and β-cell function and response to lifestyle intervention among Latino youth with obesity." (PMID 37299403, 2023). "Second, chronic inflammation associated with obesity and its pro-inflammatory cytokines produced by macrophages in adipose tissue can affect insulin-dependent tissues and beta cells." (PMID 37810434, 2023). "In this regard, resistin has been implied as a risk factor for dementia since it antagonizes insulin action and promotes inflammation in obesity." (PMID 37732123, 2023). "In conclusion, the present study demonstrates considerable heterogeneity in the therapeutic effect of marked (~20%) weight loss in people with obesity on insulin sensitivity, which was negatively correlated with baseline insulin sensitivity." (PMID 37159276, 2023). "PCOS has been associated with obesity, weight changes, cardiovascular diseases, and carbohydrate metabolism alterations, such as IR and insulin secretion." (PMID 36695999, 2023). "In a previous report, we showed that obesity caused prostate hyperplasia, insulin resistance, and greater contractile responses to a1-adrenoceptor agonists." (PMID 37492091, 2023). "ErbB4-null mice are susceptible to diet induced obesity, with increased fasting plasma glucose and insulin and reduced liver function." (PMID 37669858, 2023). "To understand the indexes of insulin secretion and sensitivity associated with different obesity patterns, we developed multiple linear regression models." (PMID 36909323, 2023). "After a huge amount of work during decades of research, we now understand how the inflammatory signalling cascades that are a hallmark of obesity are highly interlinked with energy homeostasis and insulin signalling." (PMID 36175539, 2023).